INS (insulin)
Diseases named in the same sentence as INS in open-access papers (continued):
Sharing a sentence is not in itself a finding about the gene and the disease.
depression (continued). "Although strict glycemic control should be achieved, patients receiving intensified treatment with insulin should be regularly screened for depression." (PMID 32637427, 2020). "Depression was related to decompensation, possibly due to forgetting or inability to take insulin or due to injection of an incorrect dose." (PMID 32488499, 2020). "Risk factors are poor blood glucose control, excessive alcohol intake, depression, eating disorders, insulin pump use in T1D patients due to infusion site complications, patient errors, or pump device malfunction." (PMID 32488499, 2020). "Reducing exposure to depression-generating factors and exercising caution while using insulin pumps are important measures." (PMID 33117456, 2020). "Only significant factors for depression were older age, homemaker, education below the secondary level, smaller family size (≤7), insulin use and additional illness." (PMID 31181109, 2019). "Although other studies have reported incidence of depression to be higher in diabetics who are dependent on insulin for their treatment, our study reported different outcomes." (PMID 31131177, 2019). "HF feeding for 16 weeks altered molecular targets of insulin signaling, innate immune system, and inflammation in hippocampus of rats, which are related to the aggravation of anxiety and depression." (PMID 31461911, 2019). "Depression was found to be significantly higher among patients who were smoking (p = 0.029) and among patients who were on insulin therapy (p = 0.026)." (PMID 30775378, 2019). "Patients on insulin therapy were almost twice as likely to have mild to moderate depression (OR 1.78 [95% CI 1.12 – 2.82], p = 0.015)." (PMID 30775378, 2019). "Screening for depression at the time of diagnosis of diabetes, during routine follow‐up visits, on initiation of insulin, during hospitalization, and at the onset of any complications can identify the symptoms of depression." (PMID 30534392, 2019). "A few trials have also reported improvement in metabolic and/or insulin sensitivity parameters alongside improvement in depression outcomes when these interventions are used as adjunctive therapy for depression." (PMID 30803432, 2019). "On regression analysis, both being a current smoker and being on insulin therapy were found to be independent predictors of mild to moderate depression among diabetic patients." (PMID 30775378, 2019). "Patients on insulin therapy were almost twice as likely to have mild to moderate depression compared to patients who were on other therapies." (PMID 30775378, 2019). "Apart from its role in modulating peripheral insulin sensitivity, PPAR-γ pathway has also been linked with depression via its evidence-based involvement in neuroinflammation and neuroplasticity." (PMID 30803432, 2019). "In this article, we briefly review possible molecular mechanisms associating defective brain insulin signaling with reward system, neurogenesis, synaptic plasticity and hypothalamic-pituitary-adrenal (HPA) stress axis in depression." (PMID 30837902, 2019). "A large-scale study of adults in the US also reported a higher rate of depression in people using insulin." (PMID 31181109, 2019). "In people with type 2 DM, greater incidence of depression was seen in insulin-dependent individuals than those who were non-insulin dependent." (PMID 31131177, 2019). "Treatment with oral metronidazole or vancomycin decreases inflammation, improves insulin signaling in the brain and reduces signs of anxiety and depression." (PMID 29910467, 2018). "Younger age, female gender, insulin use, difficulty following dietary recommendations, higher HbA1c, depression, treatment for depression and lower own health rating were associated with greater odds of interpersonal distress on adjusted analysis." (PMID 29777153, 2018).
depression (continued). "On the other hand, evidence suggests a bidirectional relationship between IR and depression risk in PCOS patients which also indicates the association between serotonin and insulin system." (PMID 30123264, 2018). "At 2 years of follow-up, both the intervention and control groups had a significantly lower mean waist circumference, insulin dose, depression score and fatigue score than at baseline (p < 0.05)." (PMID 29318342, 2018). "Secondary outcomes were HbA1c levels, insulin dose, plasma lipid levels, depression, anxiety, self-esteem, quality of life, fatigue, physical activity, eating disorders and related cognitions." (PMID 29318342, 2018). "In two previous studies, depressed, non-diabetic patients who were given either tricyclic or SSRI antidepressants and who achieved depression remission showed improved insulin sensitivity over a 5- to 8-week period." (PMID 30138433, 2018). "Six clusters were identified according to baseline variables (gender, age, insulin use, body mass index, depression history, pregabalin monotherapy, prior gabapentin, pain score, and pain-related sleep interference score)." (PMID 30521533, 2018). "Measures of psychological stress, cognitive function, blood pressure, glucose-insulin metabolism and depression will be carried out." (PMID 30027123, 2018). "For both groups, the average waist circumference, insulin dose, depression score and fatigue score remained significantly lower during follow-up after the VLCD." (PMID 29318342, 2018). "Other significant improvements were found for body mass index (p < 0.01); insulin (p = 0.02) and luteinizing hormone (p = 0.04); blood pressure (p = 0.01); quality of life (p < 0.01); depression, anxiety and stress (p < 0.01); and pregnancy rates (p = 0.01)." (PMID 28685911, 2017). "Although the use of Cordyceps spp. has been previously addressed to improve insulin insensitivity and improve the detrimental symptoms of depression; its mechanistic nature remains unsettled." (PMID 27553852, 2016). "Further studies are warranted to investigate if chronic VNS (e.g., in patients with epilepsy or major depression) reduces glucose tolerance by suppression of insulin release via afferent VNS." (PMID 26884478, 2016). "Continuation with RAI at 12 months was significantly more likely in patients with baseline A1C values 8.0–9.0% and >9.0% compared with HbA1c <8.0%, cognitive impairment, and depression and in those who added basal insulin during the 12-month follow-up period." (PMID 27761472, 2016). "Persons with both elevated levels of anxiety and depression were also less likely to start insulin therapy." (PMID 27537359, 2016). "A correlational analysis of insulin sensitivity measures with the duration and episodes of depression would be conducted when sample size is expanded, and such a project would obviously complement our current work." (PMID 27274905, 2016). "Aspects such as depression subtypes, inflammation, insulin resistance, oxidative stress, and prothrombotic states in critical brain circuits and periphery are critically appraised." (PMID 25878903, 2015). "A novel finding in our study was the observed association between higher plasma glucose/blood glucose levels, insulin resistance and suicidal behaviour in depression." (PMID 26199013, 2015). "Previous studies suggest that resistance to insulin effects on central neurons play a role in depression." (PMID 26053886, 2015). "As secondary objectives, the effects of the exercise intervention on pain, anxiety, depression, nutritional status, insulin resistance, tolerance of chemotherapy, survival, and adherence to the APA program will be evaluated." (PMID 26458923, 2015). "Secondary outcomes include change in biomarkers of inflammation, oxidative stress, lipid metabolism, glucose, insulin, blood flow velocity, and psychological well-being factors (i.e. stress, sleep, anxiety, depression)." (PMID 25928696, 2015).
depression (continued). "The present study aimed to establish a stress-depression model in mice to further study the effects of stress-induced changes upon insulin sensitivity and behavioural consequences." (PMID 25310187, 2014). "A study reported that delayed initiation of insulin in type 2 makes a significant number of diabetic patients vulnerable to diabetic complications and its adverse outcomes, including depression." (PMID 24524353, 2014). "Factors associated with both MCI and depressive syndrome were female gender, single marital status, past smoking status, retinopathy, previous CVD or stroke, increased number of comorbidities, and insulin treatment." (PMID 25431771, 2014). "The hypothesis that depression is associated with delayed initiation of insulin therapy merits more thorough testing, preferably in studies where more information is available about patient-, provider- and health care system factors that may influence the decision to initiate insulin." (PMID 24223860, 2013). "We have previously performed four large RCTs with high dose vitamin D intervention in Tromsø, northern Norway, studying specifically the effects on weight, insulin sensitivity, bone density, and depression scores." (PMID 23577264, 2013). "Other factors have been shown to affect cortisol levels in children, such as weight, insulin sensitivity, circadian rhythms, transcortin levels, sleep-wake cycles and stress factors like anxiety and depression." (PMID 23748059, 2013). "As with other studies, insulin use predicted greater depression, with insulin likely a proxy for greater disease severity." (PMID 24238561, 2013). "Data were pooled from four randomized clinical trials with vitamin D performed in Tromsø with weight reduction, insulin sensitivity, bone density, and depression scores as endpoints." (PMID 23577264, 2013). "Women with undifferentiated depression had significantly higher fasting glucose and insulin and HOMA index." (PMID 22235252, 2012). "XYS/RTSES improved the regulation of blood glucose and increased the insulin sensitivity in reserpine-induced anxiety and depression." (PMID 23134744, 2012). "The XYS/RTSES significantly elevated the shuttle activity, reduced the immobility time on TST and FST, also improved the regulation of blood glucose and increased the insulin sensitivity in reserpine-induced anxiety and depression in mice." (PMID 23134744, 2012). "For both models (PHQ-9 and WHO-5); female sex, lower income, older age, patients with combined insulin and oral therapy, co-morbid heart disease and a higher number of co-morbidities were all found to be independent predictors for depression." (PMID 22909306, 2012). "The combined results from the OGTT and ITT suggest that XYS/RTSES increases the insulin sensitivity in reserpine-induced depression." (PMID 23134744, 2012). "Although many of the comorbidities and medications had similar rates between the two cohorts, those in the Birmingham Own Health cohort reported lower rates of asthma and COPD, although higher rates of depression, use of diuretics and insulin." (PMID 21929804, 2011). "Induction of oxidative stress also increases blood insulin levels, an additional factor pertaining to acne and depression which we will discuss shortly." (PMID 21143923, 2010). "In those who took oral medication, the percentage of depression was 18.5% (10/54) and in those who were treated by insulin the percentage was 39.1% (18/46)." (PMID 20535315, 2010). "In those who took oral medications, the percentage of depression was 18.5% (10/54) and in those who were treated with insulin the percentage was 39.1% (18/46)." (PMID 20535315, 2010). "For depression, the analyte that showed the highest difference between cases and control was insulin (in particular for female subjects)." (PMID 20161799, 2010). "For depression, the insulin elevation in patients compared with controls remains highly significant after fitting BMI, as well as across different BMI ranges (not shown)." (PMID 20161799, 2010).
depression (continued). "For some protein analytes, the observed change is clearly more marked in one of the disease groups, such as in the case of BDNF and EGF for schizophrenia and insulin for depression." (PMID 20161799, 2010). "In depression, univariate analysis highlighted a significant difference in particular for insulin and matrix metallo-proteinase 9 (MMP-9), which was also highlighted by the multivariate approach." (PMID 20161799, 2010). "Patients treated with insulin had higher depression and lower general well-being scores than patients treated with oral antidiabetic agents and diet." (PMID 20626879, 2010). "In summary, our study provides a homogenous condition to clarify the glucose-insulin homeostasis in relation to depression and antidepressant treatment." (PMID 20490354, 2010). "The depression score improved significantly in patients switched to insulin treatment compared with patients remaining on insulin therapy." (PMID 20920319, 2010). "Findings also suggest an overlapping pathophysiology between depressive disorder and insulin regulation." (PMID 20490354, 2010). "The study found that among the patients on insulin therapy, likelihood of depression increased with the increased impairments in IADLs." (PMID 17683531, 2007). "The most common antidiabetic medications for patients with neuropathy and depression were metformin (59.44%), insulin lispro (36.16%), glyburide (29.43%) and glipizide (26.65%%)." (PMID 17059602, 2006). "If so, then improving insulin sensitivity could be an effective means of reducing depression symptoms." (PMID 41503521, 2026). "Current evidence suggests that chronic low‐grade inflammation, oxidative stress, impaired antioxidant defence mechanisms, and insulin resistance may contribute to the development of psychiatric disorders, including depression." (PMID 41574026, 2026). "Our post hoc secondary analyses suggest that associations with metformin and insulin prescribing may differ by SMI disorder, with findings differing for schizophrenia as compared to bipolar disorder and major depression." (PMID 41235789, 2026). "It suggested that reduction of dietary fat could improve HFD-induced depression-like behavior, potentially through mechanisms involving improved insulin signaling and normalization of lipid homeostasis." (PMID 40710585, 2025). "In addition, although we observed a significant relationship between insulin use and depression among patients with good glycemic control, we were not able to present stratified data by HbA1c levels across different depression severity categories." (PMID 40429455, 2025). "Also, a statistically significant relationship was found between Beck depression groups and intensive insulin treatment (basal plus bolus insulin treatment) (p = 0.005)." (PMID 40429455, 2025). "The 25 (OH)D level was positively correlated with age, albumin, Hb, ALT, T-bil, calcium, PCS, MCS, and CCI, and negatively correlated with TG, insulin, HOMA_IR, PLT, eGFR, phosphorus, iPTH, the HBM score and depression scores in the univariate association analysis." (PMID 40618164, 2025). "Additionally, the basal plus bolus insulin ratio in the normal and mild depression groups was lower than that in the moderate depression group (p < 0.05)." (PMID 40429455, 2025). "Notably, the basal plus bolus insulin ratio was lower in the normal and mild depression groups compared to the moderate depression group." (PMID 40429455, 2025). "When the model is evaluated in general, it is seen that both demographic and metabolic parameters make significant contributions to depression scores; especially female gender, age, BMI, postprandial blood sugar, and the types of insulin treatment applied are important predictors." (PMID 40429455, 2025). "Similarly, depression levels were found to be significantly higher in individuals using basal insulin (B = 5.85; p < 0.001) and intensive insulin therapy (B = 8.73; p < 0.001)." (PMID 40429455, 2025).
depression (continued). "In summary, antidepressants such as escitalopram and citalopram may affect glucose metabolism by addressing stress and depression, which are recognized factors affecting insulin sensitivity and glucose regulation." (PMID 40600014, 2025). "If such a link exists, lifestyle interventions may hold promise for reducing inflammation and increasing insulin sensitivity in individuals with depression characterized by IMD symptoms." (PMID 41436766, 2025). "Integration of CGM data in EHRs with adjunct data from fitness and sleep trackers, meal‐planning apps, connected insulin pens and other PROs, such as anxiety and depression, may further improve management of people with T2D in primary care." (PMID 39676327, 2025). "The hypothalamic–pituitary–adrenal (HPA) axis is commonly hyperactive in depression, yet the consequent hypercortisolaemia is not only responsible for altered brain function, but also for metabolic disturbances, such as insulin resistance and increased adiposity." (PMID 41375608, 2025). "When evaluated in terms of insulin treatment types, it was determined that individuals who received mixed insulin (B = 5.08, p < 0.001), basal insulin (B = 5.44, p < 0.001), and intensive insulin treatment (B = 7.95, p < 0.001) had significantly higher depression scores." (PMID 40429455, 2025). "However, providing an insulin pump to youth with depression has historically been considered risky given the potential for self-harm via exogenous insulin administration." (PMID 40460446, 2025). "Insulin treatment types were also among the important variables affecting depression scores." (PMID 40429455, 2025). "According to the literature, there is limited evidence suggesting that depression could be a potential side effect of insulin, biguanides, and/or sulfonylureas." (PMID 40429455, 2025). "Although the small sample size makes it difficult to draw definitive conclusions, the positive impact of choline alphoscerate use on insulin resistance parameters might be more significant when choline alphoscerate improves depression symptoms." (PMID 40095622, 2025). "Furthermore, a significant relationship was found between depression severity and intensive insulin treatment (basal plus bolus insulin therapy)." (PMID 40429455, 2025). "The use of mixed insulin was more prevalent in the moderate and severe depression groups than in the normal or mild depression groups, highlighting that depression might contribute to more complex insulin regimens." (PMID 40429455, 2025). "This could be due to hormonal changes throughout their lifespan and experience of higher levels of stress, depression and anxiety compared with men, which can affect insulin sensitivity and glucose metabolism." (PMID 41395632, 2025). "However, in patients with depression from western countries, hypersomnia and hyperphagia were found to be positively associated with HOMA-IR or level of insulin." (PMID 38783222, 2024). "In addition, insulin levels were found to influence dopamine and other crucial neurotransmitters related to the phenomenology and management of major depressive disorder." (PMID 38463431, 2024). "Overall, our results suggest that the association between depression, ICV, and the volumes of subcortical brain structures could be explained by the dysfunction of the insulin signaling pathway, leading to a reduction of dopamine and monoamines levels." (PMID 40800518, 2024). "Based on these findings, we hypothesize that irisin may serve as a regulator of energy metabolism, particularly glucose metabolism and insulin activity, in patients with depression." (PMID 39484160, 2024). "Finally, behavioral factors in individuals with depression, such as poor diet, sedentary lifestyle, smoking and alcohol consumption, can have a direct impact on fertility by affecting body weight, insulin sensitivity, and overall hormonal balance." (PMID 39280012, 2024).